FGF19 (fibroblast growth factor 19)
Diseases named in the same sentence as FGF19 in open-access papers (continued):
Sharing a sentence is not in itself a finding about the gene and the disease.
tumor (132 papers, 2009 to 2026). "This overexpression of FGF19 is strongly associated with advanced tumor stages, including tumor-node-metastasis, extrathyroidal extension, lymph node involvement, and distant metastasis." (PMID 41328353, 2026). "FGF19 plays a crucial role in various cancers, with its aberrant activation closely linked to tumor initiation, progression, and metastasis." (PMID 41328353, 2026). "In this section, we aim to dissect the potential mechanisms underlying FGF19-driven tumor metabolic reprogramming." (PMID 41328353, 2026). "In contrast, the PI3K/AKT pathway activation is caused by FGF19 overexpression, which counteracts the anti-tumor effects of lenvatinib." (PMID 41328353, 2026). "Inhibiting FGF19 or its associated signaling pathways can slow tumor growth and metastasis by reducing the proliferation, migration, and invasion of BC cells." (PMID 41328353, 2026). "Under vitamin D monotherapy, NK cells showed suppression of pathways associated with tumor-promoting signaling, including genes, such as FGF19 and LINC00698." (PMID 41515234, 2025). "Lenvatinib inhibits fibroblast growth factor (FGF) receptors 1–4, and FGF19 is a tumor biomarker of lenvatinib‐susceptible HCC." (PMID 35302279, 2022). "In this study, we investigated the potential of serum FGF19 as a novel tumor marker of HCC based on a sandwich enzyme-linked immunosorbent assay (ELISA)." (PMID 31718608, 2019). "Upregulated FGF19 expression in human HCC specimens was found to be associated with tumor progression and poor prognosis." (PMID 29973237, 2018). "Encouragingly, this study offers the advantages of the translational approach in mice and humans, and further effort is worthy and needed to study the FGF19/FGFR4 axis linked to tumor-initiation in human HCC." (PMID 29973237, 2018). "In concurrence with this, tumour progression in HCC patients is associated with increased FGF19 expression, and FGF19 gene has been shown to be a driver gene for HCC." (PMID 28178326, 2017). "An association of FGF19 m RNA expression in the tumour with disease free survival and overall survival has also been reported." (PMID 28943626, 2015). "FGF19 amplification was present in 5% of tumours and it was significantly associated with cirrhosis (p = 0.017)." (PMID 28943626, 2015). "High FGF19 expression is associated with reduced proportions of immune cells and may drive tumor progression by suppressing immune activity." (PMID 41328353, 2026). "Furthermore, amplified FGF19 is closely associated with lower 5-year OS (overall survival), along with a larger tumor size, multiple tumors, and microvascular invasion." (PMID 33802841, 2021). "This beneficial host response may, however, come at the expense of cell proliferation, tumour initiation and progression associated with prolonged exposure to elevated FGF19 levels." (PMID 28508871, 2017). "Our findings provide novel mechanistic insight into tumor aggressiveness that is associated with MT-mediated upregulation of FGF19/FGFR4 signaling axis, suggesting that inactivating this molecular node may help actualize the promise of MT supplements in cancers." (PMID 33691750, 2021). "FGF19 is emerging as a potential oncogenic driver in TC, with studies suggesting its role in tumor progression." (PMID 41328353, 2026). "A deeper understanding of the interplay between FGF19 signaling, the tumor microenvironment and systemic metabolism will be essential to unlock its potential for precision oncology." (PMID 41328353, 2026). "A thorough understanding of these mechanisms is anticipated to reveal the oncogenic potential mediated by FGF19 via tumor metabolism and to offer new directions for the development of feasible therapeutic strategies." (PMID 41328353, 2026). "Upon interacting with tumor cells, FGF19 activates specific transcription factors, which are subsequently bound to the promoter regions of MMP-encoding genes." (PMID 41328353, 2026).
tumor (continued). "Tumor growth and progression can be driven by FGF19 overexpression in HCC through the FGF19/FGFR4 signaling pathway." (PMID 41328353, 2026). "Enteroendocrine effects of tumor-derived FGF19, including suppression of bile acid synthesis, are evident in liver samples via RNA sequencing and validated by RT-PCR." (PMID 41631414, 2026). "FGF19 exerts a significant impact on promoting tumor cell proliferation primarily through the activation of the FGFR4 signaling pathway." (PMID 41328353, 2026). "FGF19 overexpression is often observed in various cancers, and its contribution to tumor progression is primarily mediated through the activation of FGFR4, although the specific mechanisms and outcomes differ among cancer types." (PMID 41328353, 2026). "In this section, we aim to dissect the tumor-specific mechanisms by which FGF19 contributes to oncogenesis and tumor progression in various cancers." (PMID 41328353, 2026). "The PI3K/AKT signaling pathway, which is vital for the proliferation and survival of tumor cells, can be activated by FGF19." (PMID 41328353, 2026). "The formation of neutrophil extracellular traps, which are fibrous structures released by neutrophils that can encapsulate tumor cells and thereby shield them from immune cell attack, can be promoted by FGF19." (PMID 41328353, 2026). "In tumor cells, it has been demonstrated that FGF19 can activate downstream signaling pathways, including the FGFR4-ERK pathway, to promote the expression of key enzymes involved in fatty acid synthesis, such as FASN and ACC." (PMID 41328353, 2026). "FGF19 is upregulated in GC and correlates with factors including tumor invasion depth, lymph node involvement, and TNM staging." (PMID 41328353, 2026). "In vivo experiments have demonstrated that U3-1784 significantly inhibits tumor growth in ten different HCC models with overexpressed FGF19, achieving an inhibition rate of up to 90%." (PMID 41328353, 2026). "FGF19 plays a crucial role in shaping the tumor microenvironment through its interactions with various cell types." (PMID 41328353, 2026). "A comprehensive understanding of the specific mechanisms of FGF19 in tumor metabolism is essential for developing more effective therapeutic approaches." (PMID 41328353, 2026). "Given the overexpression of FGF19 in TC tissues and its strong correlation with tumor malignancy, FGF19 holds significant potential as a molecular marker for early TC diagnosis." (PMID 41328353, 2026). "Future research should focus on elucidating the detailed mechanisms through which FGF19 interacts with various signaling pathways and networks in different tumor types." (PMID 41328353, 2026). "In rhabdomyosarcoma (RMS), elevated expression levels of FGF19 are typically observed compared to those in normal tissues, and this expression is positively correlated with increased tumor invasiveness and malignancy." (PMID 41328353, 2026). "In summary, the mTOR pathway is activated by FGF19, which drives metabolic reprogramming in tumor cells and supports their growth and proliferation." (PMID 41328353, 2026). "In tumor metabolism, the regulation of amino acid metabolism by FGF19 through multiple mechanisms has been shown to influence tumor cell growth and proliferation." (PMID 41328353, 2026). "Silencing FGF19 in PCa cells that express autocrine FGF19 results in reduced invasion and proliferation in vitro, as well as tumor growth in vivo, highlighting its oncogenic potential." (PMID 41328353, 2026). "For instance, in LUSC, a correlation exists between high FGF19 expression and mTOR activation, enhancing glucose and amino acid uptake, glycolysis, and oxidative phosphorylation to support tumor growth." (PMID 41328353, 2026). "Given its key role in amino acid metabolism and tumor development, the FGF19 signaling pathway, particularly FGFR4, has been regarded as a potential therapeutic target." (PMID 41328353, 2026).
tumor (continued). "The inhibition of the mTOR pathway can block this process, providing a basis for combined therapeutic strategies targeting FGF19 and mTOR, offering a new direction for tumor treatment, particularly in targeting tumor metabolism." (PMID 41328353, 2026). "FGF19 also modulates the recruitment and polarization of immune cells within the tumor microenvironment." (PMID 41328353, 2026). "Specifically, in the context of HCC, FGF19 has been shown to interact with the Wnt/β-catenin pathway, further promoting tumor progression through cross-talk mechanisms that enhance the oncogenic potential of both signaling networks." (PMID 41328353, 2026). "Overall, the cross-talk between FGF19 and these signaling pathways plays a complex yet crucial role in tumor development and progression." (PMID 41328353, 2026). "It has been found in studies that the anti-tumor effects of lenvatinib are enhanced by FGF19 depletion, through the reduction of p-PI3K and p-AKT expression." (PMID 41328353, 2026). "FGF19 is capable of promoting angiogenesis, which is essential for tumor metastasis, by stimulating VEGF production in both HCC and stromal cells." (PMID 41328353, 2026). "In preclinical experiments, HS236 demonstrated significant inhibitory effects on the proliferation of FGF19-positive tumor cells in vitro by selectively binding to the FGFR4 target in tumor cells and blocking its function." (PMID 41328353, 2026). "Inflammatory cancer-associated fibroblasts (iCAFs) induced by FGF19 can secrete immunosuppressive factors such as interleukin-10 (IL-10) and transforming growth factor-β (TGF-β), which dampen anti-tumor immune responses." (PMID 41328353, 2026). "Given the central role of FGF19 in regulating the Wnt/β-catenin pathway and its downstream metabolic effects, the targeting of FGF19 represents a promising therapeutic strategy for modulating tumor metabolism." (PMID 41328353, 2026). "Lenvatinib was recommended to four patients with FGF19 amplification; this agent has a reported anti-tumor effect in FGF19-driven HCC." (PMID 39541004, 2025). "Ninety-six percent of 53 IHC FGF19-positive tumours were assessed for FGFR4 and KLB mRNA expression." (PMID 40205008, 2025). "In CRC, fibroblast growth factor 19 (FGF19) derived from tumour cells can induce the formation of iCAFs through the FGFR4-JAK2-STAT3 pathway." (PMID 39780187, 2025). "FGF19 analogs, designed to mimic the natural ligand while avoiding its tumor‐promoting effects, have demonstrated anti‐fibrotic and anti‐tumor properties by suppressing BAs synthesis and modulating downstream signaling pathways." (PMID 40314129, 2025). "In HCC, FGF19 overexpression promotes tumor progression and poorer prognosis by activating the Wnt/β‐catenin signaling pathway, which drives cell proliferation and survival." (PMID 40314129, 2025). "FGF19-positive patients showed radiographic tumour shrinkage and a trend for better responses to FGFR4 inhibitors." (PMID 40205008, 2025). "Dose-dependent responses observed with fisogatinib, demonstrated FGF19-positive tumours as the responsive population." (PMID 40205008, 2025). "FGFR4-directed agents show activity in FGF19-positive tumours, yet resistance mechanisms argue for refined biomarkers and rational combinations." (PMID 41301037, 2025). "In previous studies, CCL-28, FGF-19 and IL-2 were mostly investigated in immune disorders and tumor treatment 51-54, and neurturin was mainly discussed in muscular, neurodegenerative and psychiatric disorders 55,56." (PMID 40225870, 2025). "The FGF family consists of numerous ligands and receptors that contribute to various aspects of tumor biology, with FGF19 and its receptor FGFR4 emerging as key players in CRC pathogenesis." (PMID 41002393, 2025). "FGF19-expressing cholangiocytic tumor cells have a selective growth advantage over hepatocytic tumor cells over multiple passages in a culture system." (PMID 40684183, 2025).
tumor (continued). "In the SOX4-expressing components of the tumor, a subset of cells with higher nuclear β-catenin levels and cholangiocytic markers express FGF19, which promotes proliferation of surrounding HNF4A-expressing hepatoblastic cells." (PMID 39567523, 2024). "We found that foci of FGF19 expression co-localized with tumor cells that were HNF4A-KRT19+, which we denote as cholangiocytic." (PMID 39567523, 2024). "By contrast, FGF19 expression was detected by Smart-3SEQ in only 1 of 15 independent fetal tumor specimens (7%) and 1 of 15 normal liver specimens (7%)." (PMID 39567523, 2024). "As FGF19 tumor-promoting effects were observed in the context of cooperation with MYC or β-catenin, both of which have a documented pro-mitogenic activity, our result suggests that they are unlikely to be solely based on stimulation of cell proliferation." (PMID 38228803, 2024). "In accordance with these studies, we found that FGF19 levels were higher in the serum of NPC patients and had a close relationship with tumour stage, supporting the importance of FGF19 in NPC diagnosis." (PMID 37782406, 2024). "In our model, the co-expression of FGF15 with MYC also gave rise to hepatic carcinogenesis, albeit within a slightly longer timeframe (7/8 mice exhibited tumors after 4–6 weeks post-HGT) and a lower tumor burden (mean = 10.3) in comparison with FGF19 + MYC." (PMID 38228803, 2024). "It was therefore of interest to assess possible tumor promoting effects of oncogenic combinations involving FGF19 and its analogs." (PMID 38228803, 2024). "Through functional studies in prospectively obtained patient-derived tumoroids, we identify FGF19 as a context-specific target of Wnt in tumor cells with biliary differentiation marked by the embryonic transcription factor SOX4." (PMID 39567523, 2024). "FGF19/FGFR‐mediated ETV4 increases the expression of PD‐L1 and chemokine CCL2 in HCC, leading to the accumulation of tumor‐associated macrophages (TAMs) and MDSCs, suppression of CD8+ T cell activity, and promotion of HCC metastasis." (PMID 38318160, 2024). "Instead, the combination of constitutive Wnt pathway activation and Wnt/β-catenin-dependent FGF19 together allow these tumor cells to progress through the cell cycle and form colonies in the absence of exogenous growth factors." (PMID 39567523, 2024). "An intriguing observation is the expression of FGFR4 in the fetal tumor cells and its ligand FGF19 in the embryonal tumor cells, suggesting crosstalk between the two subtypes." (PMID 39567475, 2024). "Among 12 independent embryonal tumor components (from different patients) that were dissected and analyzed by Smart-3SEQ, 9 specimens (75%) showed evidence of FGF19 expression by RNA sequencing." (PMID 39567523, 2024). "Strikingly, cells expressing FGF19 characteristically clustered within regions of embryonal histology with multiple FGF19-expressing foci appearing in the same tumor, at varying distances from each other." (PMID 39567523, 2024). "Nevertheless, FGF19 remained an attractive candidate for treatment of metabolic disease, prompting the development of analogs uncoupling its metabolic and tumor-promoting activities." (PMID 38228803, 2024). "Here, we uncover an epigenetic program whereby HMGA1 upregulates FGF19 during tumor progression and stroma formation." (PMID 36919699, 2023). "Together, our findings reveal a unique role for HMGA1 in tumor progression and “building” a stromal wall through FGF19 and highlight a new therapeutic target for a subset of highly recalcitrant tumors." (PMID 36919699, 2023). "VEGF and FGF cooperate in angiogenesis in vitro and in vivo.VEGF is synergistic with FGF19 in neoplastic disease." (PMID 36927328, 2023). "The expression of FGF19 was related to lymphatic metastasis and abdominal and distant metastasis (p = 0.001, p = 0.028, respectively), and high expression of FGF19 was more prone to tumor metastasis." (PMID 36751636, 2023).
tumor (continued). "Taken together, these results indicate that HMGA1 drives PDAC tumor initiation, progression, and stroma formation, at least in part, by inducing FGF19 expression and secretion." (PMID 36919699, 2023). "It has been observed that FGF19, as a growth factor, can stimulate tumor growth and invasion and promote several cancer types, including breast, prostate and colon cancer." (PMID 37015932, 2023). "RNA sequencing revealed HMGA1 transcriptional networks governing proliferation and tumor-stroma interactions, including the FGF19 gene." (PMID 36919699, 2023). "Our results reveal what we believe is a new paradigm whereby HMGA1 and FGF19 drive tumor progression and stroma formation, thus illuminating FGF19 as a rational therapeutic target for a molecularly defined PDAC subtype." (PMID 36919699, 2023). "More importantly, we used an FGF19‐neutralizing antibody for the clearance of tumor‐secreted FGF19, which completely blocked the promoting effect of FGF19 on CRLM." (PMID 37345586, 2023). "In xenograft tumorigenesis with E3LZ10.7 and AsPC-1 cells, both of which express higher levels of FGF19, the knockdown of FGF19 decreased tumor volumes and tumor-initiating cells." (PMID 36919699, 2023). "In mice with human PDAC xenografts, silencing HMGA1 or FGF19 depletes tumor-initiating cells while disrupting tumor growth and stroma formation." (PMID 36919699, 2023). "Given this robust upregulation and because growth factors can function in cell-autonomous and tumor-stroma interactions, we focused on FGF19 first." (PMID 36919699, 2023). "In this study, we demonstrate the functional role of tumor‐secreted FGF19 in the liver metastasis of CRC by inducing iCAF formation and subsequent NETosis in liver metastatic niches." (PMID 37345586, 2023). "Surprisingly, disrupting FGF19 via gene silencing or the FGFR4 inhibitor BLU9931 recapitulates most phenotypes observed with HMGA1 deficiency, decreasing tumor growth and formation of a desmoplastic stroma in mouse models of PDAC." (PMID 36919699, 2023). "Circulating FGF19 concentration is decreased in NASH patients, but FGF19 can also stimulate tumour progression through activating STAT3 pathway." (PMID 37361533, 2023). "FGF19 was expressed in both nucleus and cytoplasm, and the expression of FGF19 in tumor tissues was higher than that in normal tissues." (PMID 36751636, 2023). "In the mice model of LUSC with exogenous or endogenous overexpression of FGF19, we observed a significant suppression in tumor growth with combination treatment." (PMID 35463335, 2022). "Abnormal expression of FGF19-FGFR4 has been shown to accelerate hepatocarcinogenesis and metastasis, while inhibition of the FGF19/FGFR pathway augments tumor-suppressive activity and improves the prognosis in patients with HCC14,15." (PMID 36572736, 2022). "FGF401 (roblitinib) is a reversible, covalent, potent and highly selective FGFR4 inhibitor with antitumor activity in FGF19/FGFR4-dependent tumor models." (PMID 35655320, 2022). "FGF401 showed anti-tumor activity in HCC cell lines expressing FGF19 and FGFR4 on their surface like Huh7, SNU878, and Hep3B and xenografts." (PMID 36080304, 2022). "Analysis of FGF19 expression and genome-wide transcriptome analysis in tumor samples indicated a trend for better responses in patients whose tumors were FGF19 IHC positive." (PMID 35655320, 2022). "FGF19 mRNA expression was highly upregulated and correlated with tumor DC and EC and organoids B-, D- and E-TO." (PMID 35853873, 2022). "It exhibited outstanding anti-tumor activity in FGF19-expressing HCC cell lines with FGF19 amplification and intact FGFR4, as well as xenograft models with an intact FGFR4/KLB signaling pathway." (PMID 36080304, 2022). "In the present study, we have provided more data indicating that FGF19 acts as a tumor promoter in LUSC." (PMID 35463335, 2022).